BRAF (B-Raf proto-oncogene, serine/threonine kinase)
Diseases named in the same sentence as BRAF in open-access papers (continued):
Sharing a sentence is not in itself a finding about the gene and the disease.
tumor (continued). "Somatic testing showed that the tumor of one (7%) patient in the ”same region” cohort and one (17%) patient in the “different regions” cohort had activating BRAF mutations." (PMID 38893072, 2024). "By using the genetic selection method, the minimal set of variables related to BRAF mutations was defined and included 6 variables: age, primary tumor location, histological type, ulceration, LVI, and association with nevi." (PMID 39735251, 2024). "Although less than 2% of all CRC patients harbour class II and III BRAF mutations, individuals within this subgroup exhibit distinctive clinicopathological features, such as left‐sided primary tumours and well‐differentiated histology." (PMID 39073010, 2024). "Reduced levels of circulating ctDNA are linked to a smaller tumor burden and are often indicative of better clinical responses to therapies, particularly with BRAF inhibitors." (PMID 39766118, 2024). "Panel-based NGS has gained popularity for the ability to simultaneously test multiple genes, including BRAF, for both V600E and non-V600E mutations, which is more cost-effective than sequential single-gene assays and uses relatively little tumor tissue." (PMID 38627602, 2024). "In this cohort where infiltration of cytotoxic T cells was assessed on a semi-quantitative scale (score 1-4), immune cell infiltration by BRAF mutation was found mainly linked to MSI tumours." (PMID 38040818, 2024). "The difference in frequency of non-V600E BRAF mutation between CRC and non-CRC GI malignancies is important to consider, recognizing variation in tumor behavior by class of BRAF mutation." (PMID 38791902, 2024). "The sequencing of the F1 (MSO) and F2 (PTC) probands’ tumours unveiled somatic BRAF and HRAS variants, respectively." (PMID 38396644, 2024). "Some studies demonstrated that the BRAF mutation was associated with an extrathyroidal extension of the tumor and metastatic spread to cervical lymph nodes, while another study did not reveal this association." (PMID 39000197, 2024). "A contrasting role of KRAS and BRAF mutation on immune cell infiltration in CRC tumours has been previously suggested." (PMID 38040818, 2024). "Genomic testing (Oncomine Dx Target Test Multi-CDx system®) of precordium skin metastasis (70% tumor cell content) revealed a mutation of BRAF K601E with a variant allele frequency of 17.4%." (PMID 39040442, 2024). "Development of radiomics based models incorporating features such as texture, intensity, shape and wavelength in addition to location of tumor have shown promise in diagnosing BRAF V600E mutation." (PMID 39634188, 2024). "The combination of TERT promoter mutations and BRAF p.V600E is expected to provide a strong genetic basis for tumor aggressiveness." (PMID 38667446, 2024). "It highlights the importance of biomarkers such as mismatch repair (MMR) status, tumor budding, BRAF mutations, and immune responses in guiding personalized treatments for CRC." (PMID 39768914, 2024). "Univariate analysis, which encompassed the parameters of age, sex, ECOG PS, tumor location, tumor stage, tumor diameter, PD-L1 status, BRAF mutation, operability, and PTV volume, was performed to identify the risk factors associated with OS." (PMID 39123353, 2024). "Loss of CDX2 expression in mCRC was associated with higher risk of patient death and progression after first-line treatment, poorly differentiated tumours and the BRAF p.V600E variant." (PMID 38439814, 2024). "We identified 4 MSI-high samples, 39 KRAS/NRAS mutations, and 5 BRAF p.V600E mutations, with one case of coexistence of all three markers in a single tumor sample." (PMID 38539463, 2024). "The statistical analysis did not reveal any statistically significant difference between the tumor location and BRAF mutation (p = 0.2173)." (PMID 38541077, 2024). "C3 consisted mainly of younger patients with the classical histological subtype, BRAF mutation with gene fusion, and moderate tumor invasiveness but optimal prognosis." (PMID 38287330, 2024).
tumor (continued). "In the UCAN-validation cohort there was a significant association between high CRP levels and BRAF-mutated tumours, but a stratified analysis of CRP and MMR revealed a stronger association between CRP and MSI than with BRAF-mutation." (PMID 39613865, 2024). "As monotherapy with BRAF V600E inhibitors has been shown to cause activation of EGFR, which in turn causes tumor proliferation, current therapeutic options associate BRAF inhibitors with EGFR antibodies." (PMID 39682117, 2024). "Intrahepatic BTC patients with BRAFV600E mutations tend to have a higher tumor stage at surgery, a higher lymph node involvement, and an overall worse prognosis than the non-BRAF-mutated BTC patients." (PMID 38203795, 2024). "We performed Cox regression to examine the signature’s independence from additional clinical characteristics (age, breslow depth, gender, tumor stage, and BRAF and NRAS mutations) in the TCGA cohort." (PMID 38874871, 2024). "Out of 86 tumor samples, 40 (46.5%) harbored somatic mutations within actionable genes (BRAF: 2.3%, KRAS: 43%, NRAS: 2.3%)." (PMID 39635441, 2024). "CMS1 tumours are characterised by a proximal location, high immunogenicity, high BRAF-mutation rate, a CpG island methylator phenotype (CIMP), and display microsatellite instability (MSI)." (PMID 39613865, 2024). "The BRAF V600E mutation is known to be associated with aggressive tumor behavior, recurrence, and poor progression of PTC." (PMID 38341587, 2024). "NGS (Tempus xT platform) from the resected tumor revealed BRAF V600E mutation (VAF 45.6%), which was PDL1 < 1%, and microsatellite instability stable." (PMID 39234402, 2024). "Since the BRAF p.V600E mutation present in tumor samples can oscillate in the range from 50% to less than 0.1%, a diagnostic tool needs to be able to properly detect the lower mutation frequencies." (PMID 39456686, 2024). "Several studies have demonstrated high concordance between RAS/BRAF mutations detected in plasma ctDNA samples and tumor tissue in mCRC patients [1610,1611,1612,1613]." (PMID 39273409, 2024). "As BRAF/MEK inhibitor therapy tends to produce faster and higher tumor shrinkage rates in the beginning than immunotherapy, in patients with high tumor burden therapy is often initiated with targeted therapy if BRAF mutation is detectable." (PMID 39125519, 2024). "Based on 2022 guidelines from the American Society of Clinical Oncology, the decision to initiate anti-EGFR treatment should be guided by the primary tumor location and testing for BRAF and RAS (KRAS and NRAS) mutations and deficient mismatch repair or MSI2." (PMID 38347302, 2024). "The occurrence of BRAF mutations varies across different tumor sites, with higher frequencies observed in the trunk (57%), followed by the extremities (46%) and the face or scalp (28%)." (PMID 38534309, 2024). "Other mechanisms responsible for limiting T-cell trafficking in the tumor microenvironment include mutations in BRAF, and the inhibition of PTEN." (PMID 38410760, 2024). "In contrast to SGT, CGP platforms typically can evaluate many tumor agnostic biomarkers, including BRAF V600E, MMR deficiency/MSI status, TMB assessment, NTRK fusions, and RET fusions." (PMID 39544293, 2024). "The second pathological examination revealed that the tumor cells expressed CD1a, S-100, and Langerin with BRAF (c.1457_1471del) deletion mutations." (PMID 39911823, 2024). "Based on our study, there is a tendency for an increase in the percentage of BRAF mutations in tumour samples obtained from older patients or those with larger tumours or nodular infiltration." (PMID 38203733, 2024). "Tumor load surrogates, such as the BeCool score (which includes ECOG PS, tumor grading, and presence of liver, lung, or nodal metastases) and the plasmatic allele fraction of BRAF, have proven to be reliable prognostic biomarkers." (PMID 39766040, 2024).
tumor (continued). "This is a case report of a patient with G3 pancNET metastatic to the liver, lung, lymph node, and scalp (soft tissue) treated with dabrafenib/trametinib (D/T) in the presence of a BRAF V600E mutation detected in tumor tissue." (PMID 38814411, 2024). "Higher immune group had a later stage than the lower one, with a larger tumor size, increased metastasis of lymph node, and a higher frequency of BRAF mutations." (PMID 39290709, 2024). "Research suggests an association between PTC with BRAF V600E mutation and tumor volume, invasiveness and metastasis." (PMID 38607456, 2024). "Higher BRAF V600E ctDNA concentrations correlate to disease progression and initial tumor burden while lower concentrations are associated with initial treatment response and higher PFS and OS." (PMID 39156972, 2024). "BRAF inhibitors can induce tumour regression in ~50% of patients with an activating mutation of the BRAF kinase." (PMID 39409881, 2024). "For these tumour types where the prevalence of BRAF mutations is low, a phase 3 trial would be impossible to conduct, and thus, dabrafenib/trametinib should be a viable treatment option for this small subpopulation of patients." (PMID 38333370, 2024). "Association of overall survival (OS) and disease‐free interval (DFI) with preoperative plasma levels of S100B tumor marker in combination with BRAF mutation status." (PMID 39387479, 2024). "Clinical studies are also exploring the combination of ICIs with small molecule inhibitors such as Dabrafenib and Trametinib, which target the BRAF-MEK pathway in BRAF-mutated tumours." (PMID 39337605, 2024). "There was a significant association between high CRP levels and BRAF-mutated tumours in the U-CAN validation cohort." (PMID 39613865, 2024). "In this study, PIK3CA and BRAF mutations were less frequent in the rectum than in the other primary tumor locations (right and left sides)." (PMID 38409377, 2024). "Among all the tested canine carcinomas, we found BRAF-mutated tumours in the prostate (16/21), the urinary bladder (17/22), and the oral cavity epithelium (4/18), while other carcinomas tested negative." (PMID 39591358, 2024). "The BRAF mutation drives the tumor proliferation exponentially by activating mitogen-activated kinase pathway (MAP), and the development of resistance to BRAF inhibitors in both MAP kinase-dependent and MAP kinase-independent pathways." (PMID 38410760, 2024). "The analysis assessed ORR and PFS based on factors including PD-L1 expression, RAS/BRAF mutation status, primary tumor characteristics, TGF-β1 levels, pSMAD2/3 expression, and lactate dehydrogenase (LDH) levels." (PMID 39676137, 2024). "Clinical-pathological variables such as proximal tumor location, advanced age (>65 years), poor differentiation, diploid DNA content, and the BRAF V600E mutation have been found to be associated with the high prevalence of MSI-H75." (PMID 38811811, 2024). "The implications of BRAF mutation detection vary across different histological types and primary tumour sites, which highlights the need for a comprehensive investigation with a larger sample size to clarify the correlation between these factors." (PMID 39484039, 2024). "The loss of CDX2 expression in mCRC was associated with a higher risk of death and progression after first-line treatment, and with poorly differentiated tumours, and the somatic BRAF p.V600E variant." (PMID 38439814, 2024). "We analyzed the impact of BRAF V600E mutation AF on tumor invasion, co-occurring mutations, and recurrence in patients with PTC in intermediate and high-risk recurrence categories." (PMID 38607456, 2024). "In patients with an RAS (p < 0.001) or BRAF (p < 0.001) mutation at the tumor/tumor stroma transition point, significantly lower percentages of the TPS are present compared to the CPS, whose percentage is significantly larger." (PMID 38786305, 2024).
tumor (continued). "BRAF mutations are more common in tumors of the proximal colon and are associated with unique pathological features, including poorer differentiation, mucinous histology, MSI, and larger primary tumors." (PMID 39119381, 2024). "This study developed and validated a clinical prognostic model based on three factors, namely, pathological stage, microsatellite status, and primary tumor site, in patients with BRAF V600E-mutated CRC." (PMID 39464719, 2024). "In this study, 173 PTC samples were analyzed, measuring the proportion of BRAF V600E alleles by qPCR, which was then normalized against the proportion of tumor cells." (PMID 38540091, 2024). "Random forest regression models (RFs) were trained and cross-validated to predict tumor-specific MAFs from longitudinal cfDNA samples with RAS/BRAF mutations." (PMID 39433569, 2024). "It is also suggested that the BRAF mutation is an adverse prognostic factor associated with increased tumor activity and faster disease progression." (PMID 39767732, 2024). "For example, the presence of certain BRAF mutations in many tumor types is a direct target for treatment with BRAF inhibitors." (PMID 38539231, 2024). "BRAF mutation identification is important for the diagnosis and treatment of several tumor types, both solid and hematologic." (PMID 38790156, 2024). "We assessed the concordance level for NRAS and BRAF mutations between each LB analyte and the tumor tissue since these two genes are commonly screened in clinical routine." (PMID 38898234, 2024). "In patients with metastatic melanoma carrying the BRAF V600E mutation, these drugs have become instrumental in inducing tumor regression and prolonging survival in patients." (PMID 38534742, 2024). "Seven studies tested BRAF-mutated ctDNA as a marker of tumor molecular status and response to targeted therapy." (PMID 39336882, 2024). "The mechanistic difference in conjunction with the prevalent genetic aberrations such as activating BRAF mutations likely determines the response of tumor cells to MET inhibition." (PMID 38386085, 2024). "Mutations in the BRAF gene are present in various types of neoplasia and cause activation of the Ras-Raf-MEK-ERK signaling pathway." (PMID 39273371, 2024). "Loss of CDX2 expression was detected in 27 (7.8%) samples, enriched in poorly differentiated tumours (20%; p < 0.01) and in those with the BRAF p.V600E variant (40%; p < 0.01)." (PMID 38439814, 2024). "The predominant BRAF mutation, V600E, is frequently found in pediatric low-grade astrocytomas, pleomorphic xanthoastrocytomas, epithelioid glioblastomas, and other tumor types." (PMID 39606159, 2024). "Treatment outcomes for the RAS wild-type group showed three cases of SD and one PR, with the PR observed in a patient with a BRAF-mutated tumor." (PMID 39685478, 2024). "The V600E mutation in BRAF, associated with the upregulation of miR-146b, has been documented, and this association typically leads to more aggressive tumor behavior." (PMID 39036050, 2024). "Apart from the inheritable risk factor for brainstem LGG in case of NF-1, further tumor-related molecular genetic factors like several BRAF-alterations have been discovered in the last decades as prognostic factors." (PMID 39145885, 2024). "The correlation between a BRAF mutation in the results and the presence of a progressive tumor in these patients was analyzed." (PMID 39272320, 2024). "While KRAS-mutated tumours showed less infiltration of immune cells compared to wild-type KRAS tumours, in particular cytotoxic T cells and Th1 cells, BRAF-mutated tumours showed a higher infiltration of these immune cells compared to wild-type BRAF tumours." (PMID 38040818, 2024). "The presence of the BRAF mutation is associated with more aggressive tumor features, including extrathyroidal extension, advanced tumor stage at presentation, and metastasis in PTC." (PMID 38203795, 2024).
tumor (continued). "The genetic alterations in oncogenic pathways, such as mutations in genes like EGFR, KRAS, and BRAF, can impact the immune response in the tumor microenvironment." (PMID 39045411, 2024). "Here, we demonstrate that the “young” ddPCR technology is as effective as a CE-IVD marked real-time PCR method for detecting BRAF V600 hotspot mutations in tumor biopsies and recommend it for extended use in clinical settings." (PMID 38396984, 2024). "It offers an opportunity for molecular diagnostics and targeted therapeutics for dogs with BRAF-mutated tumours, as it has for humans with BRAF p.V600E tumours." (PMID 38787171, 2024). "F. nucleatum was associated with DNA mismatch repair deficiency (MMRd), BRAF:c.1799T>A p.V600E mutation, CpG island methylator phenotype, proximal tumour location, and high levels of tumour infiltrating lymphocytes (Ps < 0.01)." (PMID 38200234, 2024). "In this study, we sought to decipher the relationship between the BRAF and pTERT mutations and immune gene dysregulation in tumor samples from a cohort of 147 samples of PTC." (PMID 39717106, 2024). "After tumor progression, repeated molecular pathology revealed the BRAF V600E mutation in an almost unaltered frequency (from 6% to 2.5%), so that there was no indication of preferential growth of the BRAF-mutated clone." (PMID 38383419, 2024). "Encorafenib is a highly specific competitive inhibitor of RAF that acts solely on tumor cells expressing the BRAF V600E-mutated protein, exhibiting a more prolonged pharmacodynamic activity compared with other BRAF inhibitors." (PMID 39255538, 2024). "Previous studies have reported a higher expression of PD-L1 in tumor cells in the presence of a BRAF mutation, and further investigation is needed." (PMID 38786305, 2024). "Age, gender, tumor tissue site, pathologic stage, Breslow thickness, ulceration, BRAF and NRAS mutation status were taken into consideration." (PMID 38438381, 2024). "The tumour is usually driven by a single oncogenic variant in the MAP Kinase pathway (most frequently a KIAA1549::BRAF gene fusion)." (PMID 39294363, 2024). "No RAS variants were detected in the 2 CMTC tumors, but 1 CMTC tumor presented with the coexistence of BRAF V600E and TERT promoter variants." (PMID 38758552, 2024). "Regarding tumor localization, the highest number of BRAF mutations was found in patients with tumors on the trunk (61.5%)." (PMID 39200941, 2024). "F. nucleatum was associated with tumour characteristics related to MMRd and CRCs of the serrated pathway (e.g., right location, BRAF p.V600E, CIMP-high), consistent with previous reports." (PMID 38200234, 2024). "The combination of dabrafenib plus trametinib received tumor-agnostic approval for patients with BRAF V600E mutations." (PMID 38791902, 2024). "Downstream testing was, however, performed on only 54% (n = 1178) of these, comprising 1041 tumours tested for BRAF mutational status and a further 137 tested for MLH1 promoter hypermethylation in the absence of BRAF testing." (PMID 38355963, 2024). "Inhibition of the BRAF pathway has proven to be an effective target in multiple tumor types expressing this mutation." (PMID 39234402, 2024). "BRAF-mutated tumours tend to be aggressive and poorly responsive to chemotherapy, but despite this, a resection of CRLM can convey a survival advantage." (PMID 39001441, 2024). "Identification of BRAF mutations is of major importance in the diagnosis of several tumor types, both solid and hematologic." (PMID 38790156, 2024). "The mutation frequencies of BRAF in the tumor and blood samples were 2% and 5%, respectively, and the mutation frequencies of PI3KCA in the tumor and ctDNA samples were 5% and 0%, respectively." (PMID 38378604, 2024). "Concerning BRAF inhibition, Andrulis and colleagues examined the mutation status of BRAF V600E in primary tumor samples from 379 MM patients and correlated it with disease outcome." (PMID 39000097, 2024).